MTMR4 (myotubularin related protein 4)
Description:
Lipid phosphatase that specifically dephosphorylates the D-3 position of phosphatidylinositol 3-phosphate and phosphatidylinositol 3,5-bisphosphate, generating phosphatidylinositol and phosphatidylinositol 5-phosphate. Decreases the levels of phosphatidylinositol 3-phosphate, a phospholipid found in cell membranes where it acts as key regulator of both cell signaling and intracellular membrane traffic, in a subset of endosomal membranes to negatively regulate both endocytic recycling and trafficking and/or maturation of endosomes toward lysosomes. Through phosphatidylinositol 3-phosphate turnover in phagosome membranes regulates phagocytosis and phagosome maturation. By decreasing phosphatidylinositol 3-monophosphate (PI3P) levels in immune cells it can also regulate the innate immune response. Beside its lipid phosphatase activity, can also function as a molecular adapter to regulate midbody abscission during mitotic cytokinesis. Can also negatively regulate TGF-beta and BMP signaling through Smad proteins dephosphorylation and retention in endosomes.
Synonyms: FYVE-DSP2; KIAA0647; ZFYVE11
Tractability: Antibody: UniProt places it where antibodies can reach, with high confidence. PROTAC: UniProt records ubiquitination sites on it; ubiquitination databases record sites on it.
Gene: Protein-coding gene on chromosome 17 (58,489,529 to 58,517,905, reverse strand). Ensembl gene ENSG00000108389.
Subcellular location: Early endosome membrane; Recycling endosome membrane; Late endosome membrane; Cytoplasmic vesicle, phagosome membrane
Pathways (Reactome):
Metabolism: Synthesis of PIPs at the early endosome membrane; Synthesis of PIPs at the late endosome membrane
Signal Transduction: Downregulation of TGF-beta receptor signaling
Gene Ontology:
Molecular function: molecular adaptor activity; phosphatidylinositol-3,5-bisphosphate 3-phosphatase activity; phosphatidylinositol-3-phosphate phosphatase activity; protein binding; protein phosphatase binding; R-SMAD binding; protein serine/threonine phosphatase activity; metal ion binding
Biological process: midbody abscission; negative regulation of BMP signaling pathway; negative regulation of endocytic recycling; negative regulation of transforming growth factor beta receptor signaling pathway; phagosome maturation; phosphatidylinositol dephosphorylation; phosphatidylinositol biosynthetic process
Cellular component: early endosome membrane; early phagosome membrane; endosome membrane; extracellular region; late endosome membrane; membrane; recycling endosome membrane; cytosol; phagocytic vesicle membrane
Genetic constraint (gnomAD): Loss-of-function variants: 27 observed, 126.25 expected, observed/expected ratio (o/e) 0.21, 90% interval 0.16 to 0.29. The upper end of that interval is the gene's LOEUF score, 0.29, which puts it in group 1 of 6, group 1 being the genes least tolerant of losing a copy. Missense variants: 1,038 observed, 1,580.9 expected, observed/expected ratio (o/e) 0.66, 90% interval 0.62 to 0.69. Synonymous variants: 498 observed, 590.68 expected, observed/expected ratio (o/e) 0.84, 90% interval 0.78 to 0.91.
Homologues: Orthologues: macaque MTMR4 (98% identical), chimpanzee MTMR4 (98% identical), rabbit MTMR4 (91% identical), rat Mtmr4 (91% identical), guinea pig MTMR4 (90% identical), pig MTMR4 (90% identical), mouse Mtmr4 (90% identical), dog MTMR4 (86% identical), tropical clawed frog mtmr4 (62% identical), Drosophila melanogaster CG3632 (33% identical), Caenorhabditis elegans mtm-3 (20% identical), Drosophila melanogaster mtm (17% identical), and 9 more. Paralogues in human: MTMR3 (47% identical), MTMR2 (18% identical), SBF1 (18% identical), MTM1 (17% identical), SBF2 (17% identical), MTMR1 (17% identical), MTMR6 (16% identical), MTMR8 (16% identical), MTMR7 (16% identical), MTMR9 (13% identical), MTMR10 (12% identical), MTMR11 (11% identical), and 1 more.
Diseases named in the same sentence as MTMR4 in open-access papers:
MTMR4 is named in the same sentence as 11 diseases in open-access papers, as found by Europe PMC text mining. Sharing a sentence is not in itself a finding about the gene and the disease. The quoted sentences say what the papers report.
glioblastoma (2 papers, 2016 to 2025). The most malignant astrocytic tumor (WHO grade IV). "In grade IV glioblastomas, diffuse gliomas exhibit significant expression of MTMR4." (PMID 40894221, 2025). "Also MTMR4 expression levels were higher in grade II-III gliomas than in glioblastoma samples, in line with our RNA expression data." (PMID 27586084, 2016). "Notably, seven PTP genes (DUSP26, MTMR4, PTEN, PTPRM, PTPRN2, PTPRT and PTPRZ1) were differentially expressed between grade II-III gliomas and (grade IV) glioblastomas." (PMID 27586084, 2016).
aortic aneurysm (1 paper, 2024). A ruptured aneurysm located in the wall of the proximal portion of the descending aorta proceeding from the arch of the aorta. "MTMR4 has an effect on the development of LQT1 and aortic aneurysm." (PMID 38529329, 2024). "Though MTMR4 may affect aortic aneurysm via affecting TGFβ signaling pathway, there is no direct evidence that MTMR4 has definite curable effects on aortic aneurysm." (PMID 38529329, 2024).
breast carcinoma (1 paper, 2025). "Another possible pharmacological target for blocking breast cancer stem cells is MTMR4." (PMID 40894221, 2025).
esophageal cancer (1 paper, 2022). A primary or metastatic malignant neoplasm involving the esophagus. "Ultimately, 2 miRNAs (namely, miR-132-3p and miR-576-5p) and 4 mRNAs (namely, CAND1, ZDHHC23, AHR, and MTMR4) were obtained followed bioinformatics analyses, and possessed the potential to serve as prognostic biomarkers for radiosensitivity in esophageal cancer patients." (PMID 36456979, 2022). "The prognostic risk model based on 2 miRNAs (miR-132-3p and miR-576-5p) and 4 mRNAs (CAND1, ZDHHC23, AHR, and MTMR4) could accurately predict the prognosis of esophageal cancer patients." (PMID 36456979, 2022). "Furthermore, we uncovered that the prognostic risk model based on 2 miRNAs (miR-132-3p and miR-576-5p) and 4 mRNAs (CAND1, ZDHHC23, AHR, and MTMR4) could accurately and effectively predict the prognosis of patients with esophageal cancer." (PMID 36456979, 2022).
glioma (1 paper, 2016). A benign or malignant brain and spinal cord tumor that arises from glial cells (astrocytes, oligodendrocytes, ependymal cells). "We additionally identified PTPRT, DUSP26, PTPRN2 and MTMR4 in our screen for glioma-relevant PTPs." (PMID 27586084, 2016). "The tumor biological impact of PTPRN2 and MTMR4 may thus be context-dependent, and how these PTPs feed into glioma biology needs further investigation." (PMID 27586084, 2016). "Together with PTPs that impinge upon cellular contacts (DUSP26, PTPRZ1) and phospholipid signaling (MTMR4, PTEN and PTPRN2) they provide novel cues to explore and design glioma treatment options." (PMID 27586084, 2016).
cancer (1 paper, 2023). A tumor composed of atypical neoplastic, often pleomorphic cells that invade other tissues. "Interestingly, MTMR4 and NBPF9 currently have no clear role in cancer or response to radiation." (PMID 37771787, 2023).
infection (1 paper, 2016). The state of being infected such as from the introduction of a foreign agent such as serum, vaccine, antigenic substance or organism. "The apparent incongruence between the CFU and immunofluorescence assays earlier in the infection suggests that a proportion of the Salmonella in MTMR4-depleted cells are no longer viable." (PMID 27625994, 2016). "Cells depleted for MTMR4 were infected with RFP-SL1344 and prepared for immunofluorescent investigation or harvested for colony forming unit (CFU) assays at specific times post-infection." (PMID 27625994, 2016).
MTMR4 also shares sentences with these, for which no sentence is quoted: Atrophy (1 paper); diabetes (1); Myotubular myopathy (1); tumor (1).